DCTN1 (dynactin subunit 1)
Description:
Part of the dynactin complex that activates the molecular motor dynein for ultra-processive transport along microtubules (By similarity). Plays a key role in dynein-mediated retrograde transport of vesicles and organelles along microtubules by recruiting and tethering dynein to microtubules. Binds to both dynein and microtubules providing a link between specific cargos, microtubules and dynein. Essential for targeting dynein to microtubule plus ends, recruiting dynein to membranous cargos and enhancing dynein processivity (the ability to move along a microtubule for a long distance without falling off the track). Can also act as a brake to slow the dynein motor during motility along the microtubule. Can regulate microtubule stability by promoting microtubule formation, nucleation and polymerization and by inhibiting microtubule catastrophe in neurons. Inhibits microtubule catastrophe by binding both to microtubules and to tubulin, leading to enhanced microtubule stability along the axon. Plays a role in metaphase spindle orientation. Plays a role in centriole cohesion and subdistal appendage organization and function. Its recruitment to the centriole in a KIF3A-dependent manner is essential for the maintenance of centriole cohesion and the formation of subdistal appendage. Also required for microtubule anchoring at the mother centriole. Plays a role in primary cilia formation.
Synonyms: DP-150; DAP-150; HMND14; P135
Tractability: PROTAC: UniProt records ubiquitination sites on it; ubiquitination databases record sites on it; its protein half-life has been measured.
Gene: Protein-coding gene on chromosome 2 (74,361,154 to 74,392,087, reverse strand). Ensembl gene ENSG00000204843.
Subcellular location: Cytoplasm; Cytoplasm, cytoskeleton; Cytoplasm, cytoskeleton, microtubule organizing center, centrosome; Cytoplasm, cytoskeleton, microtubule organizing center, centrosome, centriole; Cytoplasm, cytoskeleton, spindle; Nucleus envelope; Cytoplasm, cell cortex
Subcellular location (Human Protein Atlas): Microtubules; Acrosome; Basal body; Cytokinetic bridge; Mitotic spindle; Perinuclear theca; Primary cilium
Pathways (Reactome):
Cell Cycle: AURKA Activation by TPX2; Loss of Nlp from mitotic centrosomes; Loss of proteins required for interphase microtubule organization from the centrosome; Recruitment of NuMA to mitotic centrosomes; Recruitment of mitotic centrosome proteins and complexes; Regulation of PLK1 Activity at G2/M Transition
Cellular responses to stimuli: HSP90 chaperone cycle for steroid hormone receptors (SHR) in the presence of ligand; XBP1(S) activates chaperone genes
Vesicle-mediated transport: COPI-independent Golgi-to-ER retrograde traffic; COPI-mediated anterograde transport
Disease: Signaling by ALK fusions and activated point mutants
Immune System: MHC class II antigen presentation
Organelle biogenesis and maintenance: Anchoring of the basal body to the plasma membrane
Gene Ontology:
Molecular function: microtubule binding; protein binding; protein kinase binding; sterol sensor activity; tubulin binding; tau protein binding
Biological process: axonal transport; centriole-centriole cohesion; cholesterol homeostasis; establishment of mitotic spindle orientation; lysosome to ER cholesterol transport; microtubule anchoring at centrosome; mitotic nuclear membrane disassembly; motor behavior; neuromuscular junction development; neuromuscular process; neuron cellular homeostasis; neuron projection maintenance; non-motile cilium assembly; positive regulation of microtubule nucleation; positive regulation of microtubule polymerization; positive regulation of neuromuscular junction development; regulation of mitotic spindle organization; retrograde transport, endosome to Golgi; ventral spinal cord development; maintenance of synapse structure; mitotic cell cycle; nervous system development; nuclear migration
Cellular component: cell cortex; cell cortex region; centriolar subdistal appendage; centriole; centrosome; cytoplasm; endosome membrane; intercellular bridge; kinetochore; membrane; microtubule; microtubule associated complex; microtubule cytoskeleton; microtubule plus-end; neuron projection; neuronal cell body; nuclear envelope; protein-containing complex; retromer complex; spindle; spindle pole; axon; cytosol; cell leading edge; ciliary basal body; and 1 more
Genetic constraint (gnomAD): Loss-of-function variants: 61 observed, 168.57 expected, observed/expected ratio (o/e) 0.36, 90% interval 0.29 to 0.45. The upper end of that interval is the gene's LOEUF score, 0.45, which puts it in group 1 of 6, group 1 being the genes least tolerant of losing a copy. Missense variants: 1,404 observed, 1,685.4 expected, observed/expected ratio (o/e) 0.83, 90% interval 0.8 to 0.87. Synonymous variants: 653 observed, 659.16 expected, observed/expected ratio (o/e) 0.99, 90% interval 0.93 to 1.06.
Gene-disease validity (ClinGen):
ClinGen rates the evidence that DCTN1 causes each of these diseases.
amyotrophic lateral sclerosis (autosomal dominant): Moderate. Amyotrophic lateral sclerosis (ALS) is a neurodegenerative disease characterized by progressive muscular paralysis reflecting degeneration of motor neurons in the primary motor cortex, corticospinal tracts, brainstem and spinal cord.
Homologues: Orthologues: chimpanzee DCTN1 (99% identical), macaque DCTN1 (99% identical), dog DCTN1 (98% identical), pig DCTN1 (98% identical), mouse Dctn1 (97% identical), rat C4h2orf81 (97% identical), rabbit DCTN1 (97% identical), guinea pig DCTN1 (96% identical), tropical clawed frog dctn1 (79% identical), zebrafish dctn1b (72% identical), zebrafish dctn1a (68% identical), Drosophila melanogaster DCTN1-p150 (33% identical), and 2 more. Paralogues in human: CLIP1 (13% identical), CLIP2 (11% identical), CLIP4 (11% identical), CLIP3 (8% identical).
Diseases named in the same sentence as DCTN1 in open-access papers:
DCTN1 is named in the same sentence as 79 diseases in open-access papers, as found by Europe PMC text mining. Sharing a sentence is not in itself a finding about the gene and the disease. The quoted sentences say what the papers report.
Perry syndrome (26 papers, 2013 to 2025). Perry syndrome is a rare inherited neurodegenerative disorder characterized by rapidly progressive early-onset parkinsonism, central hypoventilation, weight loss, insomnia and depression. "Mutations in the gene encoding the p150 subunit of the dynactin complex (DCTN1) are linked to amyotrophic lateral sclerosis, spinal and bulbar muscular atrophy, and Perry syndrome." (PMID 41463293, 2025). "Subsequently, mutations in DCTN1 were found to be causative in Perry syndrome and other neurodegenerative diseases." (PMID 41463293, 2025). "Perry disease (Perry syndrome) is a special hereditary subset of Parkinson’s syndrome, which correlates with the mutations in the dynactin (DCTN1) gene, while the gene products of the disease-linked DCTN1 mutants can form cytoplasmic inclusions." (PMID 39596445, 2024). "In the present study, we addressed this issue by investigating the role of DCTN1, a causative gene of Perry syndrome in which patients develop TDP-43 pathology, in the formation of TDP-43 aggregation using a Drosophila model of ALS/FTD." (PMID 38311779, 2024). "Several missense mutations in DCTN1, a subunit of the microtubule-associated motor protein complex dynactin, have been identified as the genetic cause of Perry syndrome." (PMID 38311779, 2024). "A pallido-nigro-luysian atrophy associated with TDP-43 is also characteristic of Perry syndrome, an autosomal dominant parkinsonism with central hypoventilation, caused by mutations in the dynactin subunit 1 gene (DCTN1)." (PMID 39400557, 2024). "Autosomal dominant mutations in the DCTN1 gene cause Perry syndrome, characterized by Parkinsonism, psychiatric symptoms, weight loss and central hypotension (OMIM#168605)." (PMID 37330543, 2023). "Although mutations in ATP13A2, SYNJ1, DNAJC6, FBXO7, and VPS13C act in a recessive manner, dominantly inherited mutations in DCTN1 cause Perry syndrome." (PMID 34396589, 2021). "The 46 PARK-DCTN1 patients with DCTN1 mutations linked to Perry syndrome originated from 26 families." (PMID 34396589, 2021). "Rare autosomal-dominant disease-causing variants in DCTN1 are already known for Perry syndrome (PS), motor neuron disease (ALS), and distal spinal and bulbar muscular dystrophy (dHMN7B)." (PMID 32325768, 2020). "Subsequently, a cluster of DCTN1 mutations were identified in pedigrees with Perry syndrome, PD or progressive supranuclear paralysis (PSP), suggestive of phenotypic variability of DCTN1 mutations." (PMID 26843957, 2016). "DCTN1 is associated with neuropathy, amyotrophic lateral sclerosis and Perry syndrome based on OMIM." (PMID 23597238, 2013). "Perry syndrome is caused by mutations in DCTN1, the large p150glued subunit of the dynactin complex and cell culture studies show that the disruption of dynein-mediated microtubule transport can promote TDP-43 cytoplasmic aggregation." (PMID 23666556, 2013). "To date, over 30 point mutations in the gene have been associated with the spectrum of DCTN1-related neurodegeneration, which exhibits a phenotypic spectrum, including Perry syndrome, frontotemporal dementia, amyotrophic lateral sclerosis, and progressive supranuclear palsy." (PMID 40361876, 2025). "Variants in DCTN1, encoding a protein dynactin-1, can be associated with various neurodegenerative syndromes such as Perry syndrome, Amyotrophic lateral sclerosis, Charcot-Marie-Tooth disease, distal hereditary motor neuropathy type VIIB, and frontotemporal dementia (FTD)." (PMID 33562224, 2021). "In 2009, DCTN1 mutations in multiple families of patients with Perry syndrome were discovered." (PMID 30518093, 2018). "However, the exact pathogenic mechanisms driving this neurodegeneration, as well as the diverse DCTN1-related neuropathologies associated with Perry syndrome, are unknown." (PMID 41463293, 2025).
Perry syndrome (continued). "Therefore, a direct comparison of the characteristics in iPSC-derived neurons of this mutation and those of other DCTN1 mutations may be necessary for a detailed understanding of the pathological mechanisms underlying Perry syndrome." (PMID 30518093, 2018). "DCTN1 mutations can cause familial and sporadic amyotrophic lateral sclerosis (ALS) and other neurodegenerative diseases manifesting as Perry syndrome." (PMID 41463293, 2025). "The diseases associated with DCTN1 gene mutations include ALS, ALS-FTD, atypical Parkinson’s disease, Perry syndrome, spinal and bulbar muscular atrophy, and distal hereditary motor neuronopathy type 7B." (PMID 41463293, 2025). "Four probands (2.04%) bore P/LP variants in causative genes of other diseases, including two with spinocerebellar ataxia type 2 (SCA2), one with Alzheimer’s disease (AD) (PSEN1 p.Leu282Arg), and one with Perry syndrome (DCTN1 p.Tyr78His)." (PMID 37198191, 2023). "DCTN1, firstly linked to ALS and Perry syndrome, was then associated with progressive supranuclear palsy and FTD phenotypes." (PMID 36570531, 2022). "Additionally, G59S mutant p150Glued is less stable, and both G59S and Perry syndrome-related mutant p150Glued compromise normal functions of dynactin p150Glued in a dominant-negative fashion when overexpressed, suggesting a dominant-negative mechanism for DCTN1 mutation-induced neurodegeneration." (PMID 41536567, 2022). "Several DCTN1 mutations have been described in association with ALS, degenerative parkinsonisms and Perry syndrome." (PMID 33006056, 2021). "DCTN1 in subnetwork 4 was shown to have a potentially functional relationship with neuronopathy distal hereditary motor, Perry syndrome, and amyotrophic lateral sclerosis." (PMID 30532734, 2018). "DCTN1 mutations have been associated with a familial form of ALS (p.Gly59Ser), familial progressive supranuclear palsy, Perry syndrome (p.Gly71Ala/Glu/Arg, p.Thr72Pro, and p.Gln74Pro) which is characterized by central hypoventilation and parkinsonism." (PMID 25957632, 2015). "Several studies have linked the Dctn1 protein to ALS and Perry syndrome." (PMID 36975497, 2023). "However, we are not aware of any studies analyzing mutations in the DCTN1 gene in anti-IgLON5 disease cases or, conversely, the presence of anti-IgLON5 antibodies in Perry syndrome." (PMID 39400557, 2024).
amyotrophic lateral sclerosis (16 papers, 2013 to 2025). "Reduced levels of DCTN1 mRNA and protein have been detected in patients with sporadic amyotrophic lateral sclerosis, and mutations have been linked to disease." (PMID 32138249, 2020). "Additionally, rare genetic variants in DCTN1 have been associated with other neurodegenerative disorders, such as amyotrophic lateral sclerosis (ALS), frontotemporal dementia (FTD), and syndromes resembling progressive supranuclear palsy (PSP)." (PMID 40149801, 2025). "Reduced levels of DCTN1 mRNA and protein have been found in sporadic amyotrophic lateral sclerosis (ALS) patients, and mutations have been associated with disease, but the role of this protein in disease pathogenesis is still unknown." (PMID 31291987, 2019). "Interestingly, several upregulated DE genes were related to neurodegenerative diseases, such as genes related to Alzheimer’s disease: PSEN2, TREM2, and GAB2; Parkinson’s disease: ATP13A2 and DCTN1; and amyotrophic lateral sclerosis: TAF15 and FUS." (PMID 40877796, 2025). "Variant filtering identified potentially deleterious mutations in three known disease genes: DCTN1, KIF5A and NEFH, which have been all associated with similar clinical presentations of amyotrophic lateral sclerosis, Parkinsonism and/or hereditary spastic paraplegia." (PMID 25957632, 2015). "In addition, some rare mutations in the DCTN1 gene have been associated to other neurodegenerative diseases, such as frontotemporal dementia, progressive supranuclear palsy-like syndrome and the motor neuron disease Amyotrophic Lateral Sclerosis (ALS), which results in loss of muscle control." (PMID 40589526, 2025). "Similar effect can be observed in the case of Amyotrophic Lateral Sclerosis: SOD1 has the highest betweenness centrality, followed by VCP and DCTN1 with almost twice as much lower betweenness." (PMID 25528190, 2014).
Parkinsonism (13 papers, 2015 to 2025). Characteristic neurologic anomaly resulting from degeneration of dopamine-generating cells in the substantia nigra, a region of the midbrain, characterized clinically by shaking, rigidity, slowness of movement and difficulty with walking and gait. "Regarding the DCTN1 gene, a case of parkinsonism with two trans variants has been reported, and we predict the diagnosis of more such cases in the future." (PMID 38255218, 2024). "Parkinsonism, family history, and DCTN1 mutation are sufficient to diagnose Perry disease, with an emphasis on family history." (PMID 38255218, 2024). "Dctn1 mutations may play a role in a variety of neurodegenerative illnesses, such as familial motor neuron disease, parkinsonism, and frontotemporal atrophy." (PMID 36975497, 2023). "DCTN1-associated Parkinson-plus disorder, also called Perry syndrome, is a rare autosomal dominant disorder characterized by rapidly progressive parkinsonism, depression and mood changes, weight loss, and progressive respiratory changes, chiefly tachypnoea and nocturnal hypoventilation." (PMID 35328025, 2022). "Araki found DCTN1 mutations may contribute to disparate neurodegenerative diagnoses, including familial motor neuron disease, parkinsonism, and frontotemporal atrophy." (PMID 29422030, 2018). "Recent studies also found DCTN1 variants in FTD and Parkinson’s disease." (PMID 33562224, 2021). "In Parkinson's disease, mutations of LE/lysosome proteins and motor complexes, such as LRRK2, Vps35, DCTN1, have been previously documented, suggesting that LE sorting defect and axonal transport disruption could play a causal role in this pathology." (PMID 26685126, 2016). "Moreover, atypical or complex parkinsonism may be due to mutations in genes such as ATP13A2, DCTN1, DNAJC6, FBXO7, PLA2G6, and SYNJ1." (PMID 35328025, 2022).
frontotemporal dementia (11 papers, 2018 to 2025). Frontotemporal dementia (FTD) comprises a group of neurodegenerative disorders, characterized by progressive changes in behavior, executive dysfunction and language impairment, as a result of degeneration of the medial prefrontal and frontoinsular cortices. "He subsequently underwent exome sequencing and no other mutations were found in any of the genes known to cause frontotemporal dementia apart from a variant of uncertain significance in DCTN1 (NM_004082.4: c.2264dupG: p.Ser755fs)." (PMID 31870644, 2020). "However, the variant in DCTN1 might be association with the patient’s frontotemporal dementia." (PMID 33562224, 2021). "These variants map to the CCNF, DCTN1, and NOTCH3 genes, which are involved in the ALS/frontotemporal dementia (FTD) spectrum." (PMID 36133075, 2022). "Next, we screened the genes related to Perry syndrome, frontotemporal dementia (FTD), such as DCTN1, and MAPT by Sanger sequencing and C9orf72 by the repeat-primed PCR." (PMID 32854784, 2020).
motor neuron disease (11 papers, 2015 to 2025). "We described two sporadic patients with motor neuron disease due to de novo mutations in DCTN1, c.626dupC, and c.C3823T, respectively." (PMID 32023010, 2020). "Recent studies showed that motor neuron disease-linked mutations in dynactin (DCTN1) may lead to both DCTN1 dysfunction and DCTN1 protein aggregation." (PMID 32512809, 2020). "Notably, autosomal dominant (AD) DCTN1 mutations have been reported in patients presenting with a lower motor neuron disease, ALS, and related to the ALS and FDT families." (PMID 32397312, 2020). "Moreover, dynactin (Dctn1) acting with overexpressed dynamitin (Dctn2), was shown to produce a late-onset progressive motor neuron disease inhibiting axonal transport in transgenic mice." (PMID 34946792, 2021). "A slowly progressive, ALS-like motor neuron disease, HMN7B, is indeed caused by the p.G59S mutation in DCTN1, although HMN7B does not accompany TDP-43 proteinopathy at detectable levels." (PMID 33924373, 2021).
inflammatory myofibroblastic tumor (5 papers, 2015 to 2025). A multinodular intermediate fibroblastic neoplasm that arises from soft tissue or viscera, in children and young adults. "Here, we report the case of a patient with an inflammatory myofibroblastic tumors harboring a DCTN1-ALK fusion who developed resistance to crizotinib treatment." (PMID 29872693, 2017). "To date, published case reports of DCTN1–ALK fusion solid tumors included non-small cell lung cancer (NSCLC), inflammatory myofibroblastic tumors (IMTs), Spitz tumors, and some rare types of neoplasms." (PMID 41246301, 2025). "Although detected in non-small cell lung cancer (NSCLC), inflammatory myofibroblastic tumors (IMTs), and Spitz tumors, the DCTN1–ALK fusion has not previously been reported in gastric cancer." (PMID 41246301, 2025).
COVID-19 (4 papers, 2021 to 2024). A disease caused by infection with severe acute respiratory syndrome coronavirus 2. "Both BDNF and DCTN1 have been implicated in the neurological pathology associated with COVID-19." (PMID 38632526, 2024). "GSEA of the COVID-19-related gene sets indicated that three genes namely DYNC1H1, LMNA, and DCTN1 were downregulated in human bronchial epithelial cells in COVID-19 after 24hr of infection (GSE17400)." (PMID 34832615, 2021).
dementia (4 papers, 2020 to 2023). Loss of intellectual abilities interfering with an individual's social and occupational functions. "An interesting link to monogenic dementia has recently been revealed, as DCTN1 has been found in a yeast two-hybrid screen to directly interact with APP and tau (encoded by MAPT), suggesting that these three proteins are linked at a molecular level." (PMID 37330543, 2023). "Moreover, thanks to NGS approach, we disclosed other variants in dementia-related genes, in particular FUS, ABCA7, CSF1R, DCTN1, SERPINI1 and SORL1." (PMID 33006056, 2021).